ABL1 (ABL proto-oncogene 1, non-receptor tyrosine kinase)
Description:
Non-receptor tyrosine-protein kinase that plays a role in many key processes linked to cell growth and survival such as cytoskeleton remodeling in response to extracellular stimuli, cell motility and adhesion, receptor endocytosis, autophagy, DNA damage response and apoptosis. Coordinates actin remodeling through tyrosine phosphorylation of proteins controlling cytoskeleton dynamics like WASF3 (involved in branch formation); ANXA1 (involved in membrane anchoring); DBN1, DBNL, CTTN, RAPH1 and ENAH (involved in signaling); or MAPT and PXN (microtubule-binding proteins). Phosphorylation of WASF3 is critical for the stimulation of lamellipodia formation and cell migration. Involved in the regulation of cell adhesion and motility through phosphorylation of key regulators of these processes such as BCAR1, CRK, CRKL, DOK1, EFS or NEDD9. Phosphorylates multiple receptor tyrosine kinases and more particularly promotes endocytosis of EGFR, facilitates the formation of neuromuscular synapses through MUSK, inhibits PDGFRB-mediated chemotaxis and modulates the endocytosis of activated B-cell receptor complexes. Other substrates which are involved in endocytosis regulation are the caveolin (CAV1) and RIN1. Moreover, ABL1 regulates the CBL family of ubiquitin ligases that drive receptor down-regulation and actin remodeling. Phosphorylation of CBL leads to increased EGFR stability. Involved in late-stage autophagy by regulating positively the trafficking and function of lysosomal components. ABL1 targets to mitochondria in response to oxidative stress and thereby mediates mitochondrial dysfunction and cell death. In response to oxidative stress, phosphorylates serine/threonine kinase PRKD2 at 'Tyr-717'. ABL1 is also translocated in the nucleus where it has DNA-binding activity and is involved in DNA-damage response and apoptosis. Many substrates are known mediators of DNA repair: DDB1, DDB2, ERCC3, ERCC6, RAD9A, RAD51, RAD52 or WRN. Activates the proapoptotic pathway when the DNA damage is too severe to be repaired. Phosphorylates TP73, a primary regulator for this type of damage-induced apoptosis. Phosphorylates the caspase CASP9 on 'Tyr-153' and regulates its processing in the apoptotic response to DNA damage. Phosphorylates PSMA7 that leads to an inhibition of proteasomal activity and cell cycle transition blocks. ABL1 also acts as a regulator of multiple pathological signaling cascades during infection. Several known tyrosine-phosphorylated microbial proteins have been identified as ABL1 substrates. This is the case of A36R of Vaccinia virus, Tir (translocated intimin receptor) of pathogenic E.coli and possibly Citrobacter, CagA (cytotoxin-associated gene A) of H.pylori, or AnkA (ankyrin repeat-containing protein A) of A.phagocytophilum. Pathogens can highjack ABL1 kinase signaling to reorganize the host actin cytoskeleton for multiple purposes, like facilitating intracellular movement and host cell exit. Finally, functions as its own regulator through autocatalytic activity as well as through phosphorylation of its inhibitor, ABI1. Regulates T-cell differentiation in a TBX21-dependent manner (By similarity). Positively regulates chemokine-mediated T-cell migration, polarization, and homing to lymph nodes and immune-challenged tissues, potentially via activation of NEDD9/HEF1 and RAP1 (By similarity). Phosphorylates TBX21 on tyrosine residues leading to an enhancement of its transcriptional activator activity (By similarity).
Synonyms: ABL; JTK7; c-ABL; p150; BCR-ABL; CHDSKM; bcr/abl; c-ABL1; v-abl
Tractability: Small molecule: an approved drug acts on it; a structure with a bound ligand is known; a high-quality ligand is known; it has a high-quality binding pocket; it belongs to a druggable protein family. Antibody: its Gene Ontology location is reachable by antibodies, with medium confidence. PROTAC: it is named in the literature on targeted protein degradation; UniProt records ubiquitination sites on it; ubiquitination databases record sites on it; a small molecule that binds it is known.
Target class: Tyrosine protein kinase Abl family; Protein Kinase; TK protein kinase group; Enzyme; Kinase
Chemical probes: BAFETINIB, DGY-06-116 (high quality), GNF-5 (high quality), HG-7-85-01 (high quality), HQP1351, IMATINIB, Lyn-IN-1, PD080897, PD081390, PD081991, PD082245, PD082309, PD082620, PD082919, PD083019, PD083242, PD083404, PD083560, PD083597, PD083618, and 9 more
Safety:
Unwanted effects reported when the protein is acted on. In parentheses: how it was acted on, where the effect was seen, and who reports it.
heart disease (cardiovascular system; source: Force et al. (2011))
Gene: Protein-coding gene on chromosome 9 (130,713,043 to 130,887,675, forward strand). Ensembl gene ENSG00000097007.
Subcellular location: Cytoplasm, cytoskeleton; Nucleus; Mitochondrion; Nucleus membrane (Isoform IB)
Subcellular location (Human Protein Atlas): Nucleoplasm; Nuclear bodies
Pathways (Reactome):
Gene expression (Transcription): MLL4 and MLL3 complexes regulate expression of PPARG target genes in adipogenesis and hepatic steatosis; RUNX1 regulates transcription of genes involved in differentiation of HSCs; RUNX2 regulates osteoblast differentiation
DNA Repair: HDR through Single Strand Annealing (SSA); Recruitment and ATM-mediated phosphorylation of repair and signaling proteins at DNA double strand breaks
Developmental Biology: Myogenesis; Role of ABL in ROBO-SLIT signaling
Cell Cycle: Cyclin D associated events in G1
Cellular responses to stimuli: Turbulent (oscillatory, disturbed) flow shear stress activates signaling by PIEZO1 and integrins in endothelial cells
Disease: FCGR3A-mediated phagocytosis
Hemostasis: Factors involved in megakaryocyte development and platelet production
Immune System: Regulation of actin dynamics for phagocytic cup formation
Signal Transduction: RHO GTPases Activate WASPs and WAVEs
Gene Ontology:
Molecular function: ATP binding; bubble DNA binding; enzyme activator activity; enzyme binding; four-way junction DNA binding; kinase activity; magnesium ion binding; manganese ion binding; mitogen-activated protein kinase binding; neuropilin binding; non-membrane spanning protein tyrosine kinase activity; phosphotyrosine residue binding; proline-rich region binding; protein binding; protein kinase activity; protein kinase C binding; protein serine/threonine kinase activator activity; protein serine/threonine kinase activity; protein tyrosine kinase activity; sequence-specific double-stranded DNA binding; SH2 domain binding; supercoiled DNA binding; syntaxin binding; actin monomer binding; DNA binding; and 7 more
Biological process: cellular response to hydrogen peroxide; cellular response to oxidative stress; DNA conformation change; DNA damage response; endothelial cell migration; integrin-mediated signaling pathway; intracellular signal transduction; negative regulation of double-strand break repair via homologous recombination; negative regulation of ubiquitin-protein transferase activity; neuropilin signaling pathway; phospholipase C-inhibiting G protein-coupled receptor signaling pathway; platelet-derived growth factor receptor-beta signaling pathway; positive regulation of apoptotic process; positive regulation of cytosolic calcium ion concentration; positive regulation of endothelial cell migration; positive regulation of focal adhesion assembly; positive regulation of phospholipase C/protein kinase C signal transduction; positive regulation of stress fiber assembly; positive regulation of substrate adhesion-dependent cell spreading; protein localization to cytoplasmic microtubule plus-end; regulation of actin cytoskeleton organization; regulation of axon extension; regulation of Cdc42 protein signal transduction; regulation of microtubule polymerization; response to oxidative stress; and 51 more
Cellular component: cytoplasm; cytosol; nuclear body; nucleolus; nucleoplasm; nucleus; perinuclear region of cytoplasm; protein-containing complex; actin cytoskeleton; dendrite; mitochondrion; neuronal cell body; plasma membrane; postsynapse; cell leading edge; cytoskeleton; glutamatergic synapse; growth cone; nuclear membrane; postsynaptic density; ruffle
Genetic constraint (gnomAD): Loss-of-function variants: 11 observed, 95.74 expected, observed/expected ratio (o/e) 0.11, 90% interval 0.071 to 0.19. The upper end of that interval is the gene's LOEUF score, 0.19, which puts it in group 1 of 6, group 1 being the genes least tolerant of losing a copy. Missense variants: 1,082 observed, 1,543.3 expected, observed/expected ratio (o/e) 0.7, 90% interval 0.67 to 0.74. Synonymous variants: 656 observed, 643.52 expected, observed/expected ratio (o/e) 1.02, 90% interval 0.95 to 1.09.
Cancer hallmarks: angiogenesis (promotes); invasion and metastasis (promotes); escaping programmed cell death (suppresses); proliferative signalling (promotes); genome instability and mutations (promotes); change of cellular energetics (promotes)
Homologues: Orthologues: chimpanzee ABL1 (98% identical), macaque ABL1 (97% identical), pig ABL1 (90% identical), dog ABL1 (90% identical), guinea pig ABL1 (88% identical), mouse Abl1 (86% identical), rat Abl1 (86% identical), rabbit ABL1 (85% identical), tropical clawed frog abl1 (71% identical), zebrafish abl1 (68% identical). Paralogues in human: ABL2 (54% identical), FYN (18% identical), LCK (18% identical), YES1 (18% identical), FGR (18% identical), SRC (18% identical), HCK (18% identical), PTK2 (18% identical), BLK (18% identical), FRK (18% identical), LYN (17% identical), TNK2 (17% identical), and 20 more.
Diseases named in the same sentence as ABL1 in open-access papers:
ABL1 is named in the same sentence as 352 diseases in open-access papers, as found by Europe PMC text mining. Sharing a sentence is not in itself a finding about the gene and the disease. The quoted sentences say what the papers report.
chronic myeloid leukemia (1,094 papers, 2004 to 2026). "Among BCR::ABL1 variants, micro BCR::ABL1 (μ-bcr) is the fusion of BCR exon 19 and ABL1 exon 2 (e19a2), which results in a 230-kDa protein, and can be a molecular diagnostic marker for neutrophilic-chronic myeloid leukemia (CML-N)." (PMID 41148513, 2026). "Chronic myeloid leukemia (CML) can be effectively treated inhibiting the disease-causing BCR::ABL1 kinase by tyrosine kinase inhibitors (TKIs)." (PMID 41035915, 2025). "The BCR::ABL1 fusion oncogene is not only common in ALL but represents a hallmark feature in chronic myeloid leukemia (CML)." (PMID 39966356, 2025). "Despite the groundbreaking success of tyrosine kinase inhibitor therapy, the management of chronic myeloid leukemia patients is often impaired by resistance due to specific point mutations in the BCR::ABL1 oncogene." (PMID 39996897, 2025). "BCR::ABL1 inhibitors, the treatment of choice for the majority of patients with chronic myeloid leukaemia (CML), can cause vascular side effects that vary between agents." (PMID 39009935, 2025). "Missense mutations in the BCR::ABL1 kinase domain are found in approximately 12–80% of patients with chronic myeloid leukemia (CML)." (PMID 40332324, 2025). "We first targeted the BCR and ABL1 loci to model the Philadelphia chromosome translocation associated with chronic myeloid leukemia." (PMID 40069752, 2025). "The BCR::ABL1 fusion gene is known for its association with chronic myelogenous leukemia (CML) but has also recently become its own entity in de novo acute myeloid leukemia (AML)." (PMID 38895060, 2024). "Chronic myeloid leukemia (CML) is associated with several breakpoint regions that result in different BCR::ABL1 fusion transcripts." (PMID 39183762, 2024). "ABL1 mutations, although usually specific to known resistance mutations, can be used to select alternative therapies in chronic myeloid leukemia." (PMID 38572163, 2024). "Chronic myeloid leukemia (CML) is a myeloproliferative disorder associated with a translocation that results in a BCR::ABL1 fusion gene with enhanced and deregulated tyrosine kinase activity." (PMID 38931954, 2024). "Constitutive activation of ABL1 is a hallmark of certain cancers such as chronic myeloid leukemia (CML) and is a major focus of therapeutics development." (PMID 39354505, 2024). "Chronic Myeloid Leukemia (CML) is a myeloproliferative neoplasm caused by a reciprocal translocation between the Abelson murine leukemia (ABL1) gene on chromosome 9 and the breakpoint cluster region (BCR) on chromosome 221." (PMID 38532120, 2024). "A 66-year-old Chinese female patient was diagnosed with chronic myeloid leukemia-chronic phase (CML-CP) expressing four BCR::ABL1 transcripts, including variant e16a2(V-e16a2), variant e13a2(V-e13a2), classical e13a2, and e14a2 transcripts." (PMID 39735596, 2024). "Mutational analysis of BCR::ABL1 kinase domain (KD) is a crucial component of clinical decision algorithms for chronic myeloid leukemia (CML) patients with failure or warning responses to tyrosine kinase inhibitor (TKI) therapy." (PMID 38643202, 2024). "These mutations have been extensively studied in chronic myeloid leukemia (CML) but less so in BCR::ABL1‐positive acute lymphoblastic leukemia (ALL)." (PMID 39440695, 2024). "Both classifications continued to require a 20% blast requirement for AML with BCR:ABL1 fusion to prevent diagnostic intersection with the parent disease, chronic myeloid leukemia (CML)." (PMID 39199685, 2024). "Chronic myeloid leukemia (CML) is a myeloproliferative neoplasm caused by constitutive activation of the BCR::ABL1 tyrosine kinase." (PMID 38287132, 2024). "The BCR::ABL1 is a hallmark of chronic myeloid leukemia (CML) and is also found in acute lymphoblastic leukemia (ALL)." (PMID 38970095, 2024). "BCR::ABL1 fusion is a genetic hallmark of chronic myeloid leukemia (CML) and is found in approximately 20%–50% of adult patients with acute lymphoblastic leukemia (ALL)." (PMID 38633128, 2024).
chronic myeloid leukemia (continued). "Chronic myeloid leukemia (CML) is a clonal disorder caused by the Philadelphia (Ph) chromosome encoding for the BCR::ABL1 fusion gene." (PMID 38750137, 2024). "A fusion gene breakpoint cluster region (BCR)-ABL1 is commonly associated with chronic myeloid leukemia (CML) and a subset of acute lymphoblastic leukemia (ALL)." (PMID 37627077, 2023). "A fusion oncogene known as BCR:: ABL1, was one of the first diagnostic translocations found in patients with chronic myeloid leukemia (CML) in the 1980s." (PMID 36902091, 2023). "While the clinical impact of mutations in the ABL1 gene on response to therapy in chronic phase chronic myeloid leukemia (CP-CML) is well established, less is known about how other mutations affect prognosis." (PMID 36307398, 2022). "Representative cancer-related genomic information includes epidermal growth factor receptor (EGFR) mutation in non-small cell lung cancer (NSCLC), ABL1 gene recombination in chronic myelogenous leukemia (CML), and BRAF mutations in melanoma." (PMID 35893795, 2022). "If the role of ABL1 point mutations is well-recognized in Chronic Myeloid Leukemia (CML), in ALL the prognostic relevance of detecting small clones of T315I-mutated cells at diagnosis remains to be fully elucidated." (PMID 35741115, 2022). "Chronic myeloid leukaemia (CML) is caused by BCR::ABL1, a constitutively active fusion tyrosine kinase." (PMID 36536477, 2022). "ABL1 gene mutations causes resistance to tyrosine kinase inhibitors which have been found to improve the management of chronic myeloid leukemia in humans." (PMID 29868114, 2018). "p230BCR-ABL1 is generated by the fusion of almost the entire BCR gene with the ABL1 gene and is considered a molecular diagnostic marker for neutrophilic-chronic myeloid leukemia (CML-N)." (PMID 27233483, 2016). "For example, a translocation between the TK Abl1 and the pseudokinase Bcr is closely associated with chronic myelogenous leukemia, while mutations of Src are associated with colon, breast, prostate, lung, and pancreatic cancers." (PMID 27337644, 2016). "Due to the universal presence of BCR/ABL1 rearrangement in chronic myeloid leukemia (CML), it is now defined as the diagnostic hallmark of CML." (PMID 24499728, 2014). "Translocation-mediated transcriptional activation of tyrosine kinase gene ABL1 is implicated in the pathogenesis of chronic myeloid leukemia." (PMID 21092322, 2010). "The human ortholog of Abl tyrosine kinase (ABL1) is associated with chronic myeloid leukemia and the human ortholog of Crk (CRK) is a proto-oncogene, which could plausibly be relevant to potential carcinogenic effects of 4-methylimidazole." (PMID 39497218, 2024). "Chronic Myeloid Leukaemia (CML) is caused by the BCR/ABL1 fusion gene." (PMID 26179066, 2015). "Mutations in the Abl1 gene are commonly associated with chronic myelogenous leukemia (CML) where the Abl1 gene is activated by being translocated within the Bcr (breakpoint cluster region) gene on chromosome 22, creating a new fusion gene, Bcr-Abl, that encodes an unregulated, tyrosine kinase." (PMID 24223753, 2013). "Chronic myeloid leukemia (CML) is a myeloproliferative neoplasm driven by the fusion gene BCR::ABL1, which encodes a constitutively active and targetable tyrosine kinase." (PMID 40442861, 2025). "The BCR::ABL1 fusion gene is not only a hallmark of chronic myeloid leukemia (CML) but is also present in a proportion of patients (3–5% in children, 20–30% in adults) with acute lymphoblastic leukemia (ALL)." (PMID 38970095, 2024). "Chronic myeloid leukemia (CML) is a hematological malignancy characterized by the presence of the fusion gene BCR::ABL1, which encodes a constitutively active tyrosine kinase upstream of essential cell survival and proliferation pathways." (PMID 39063200, 2024). "An atypical BCR::ABL1 fusion gene transcript in chronic myeloid leukemia (CML) patients, even those with variant Philadelphia (Ph) chromosome translocation, is very rare." (PMID 36354705, 2022).